DCLK1 (doublecortin like kinase 1)
Diseases named in the same sentence as DCLK1 in open-access papers (continued):
Sharing a sentence is not in itself a finding about the gene and the disease.
Barrett esophagus (3 papers, 2017 to 2020). Esophageal lesion lined with columnar metaplastic epithelium which is flat or villiform. "Serum DCLK1 levels were increased by > 50% in Barrett’s Esophagus (n = 9) and EAC patients (n = 14) vs controls (n = 5, p = 0.0007)." (PMID 30899515, 2019). "To determine the sensitivity and specificity of serum DCLK1, we compared levels in Barrett’s Esophagus or EAC patients before treatment to normal controls and we compared EAC patients before and after treatment." (PMID 30899515, 2019). "The analysis of this mouse model of Barrett’s esophagus provided evidence that increasing stem cell marker LGR5 and niche cell marker DCLK1 and decreasing differentiation marker (secretory mucus cells, TFF2+ cells) correlated with a high tumor score." (PMID 28930282, 2017). "Low levels of TFF2 supported the best discrimination between nondysplastic Barrett’s esophagus and Barrett’s esophagus with cancer, followed by high levels of DCLK1, low goblet ratio and high LGR5 expression." (PMID 28930282, 2017).
cardiomyopathy (3 papers, 2023 to 2025). A disease of the heart muscle or myocardium proper. "In conclusion, we identified a relationship between macrophage DCLK1 and cardiomyopathy caused by obesity." (PMID 37443105, 2023). "The present research evaluated the impact of macrophage-specific DCLK1 in the establishment of obesity-associated cardiomyopathy." (PMID 37443105, 2023). "Our study provides extensive proof that macrophage-specific DCLK1 has a deleterious impact on obesity-associated cardiomyopathy by inducing RIP2/TAK1 activation and inflammatory responses in macrophages, which subsequently promotes cardiac hypertrophy and fibrosis." (PMID 37443105, 2023). "Targeting DCLK1 may therefore be a feasible therapy or prophylactic approach for the control of cardiomyopathy caused by obesity." (PMID 37443105, 2023). "Collectively, these findings revealed that DCLK1 showed its expression in cardiomyocytes as well as macrophages, and might be associated with the pathogenesis of obesity-induced cardiomyopathy." (PMID 37443105, 2023). "In models of obesity-induced cardiomyopathy, macrophages expressing doublecortin-like kinase 1 (DCLK1) accumulated in the LV and promoted pathological remodeling by activating the RIP2-TAK1 signaling cascade." (PMID 41346626, 2025). "Cancer research has shown that DCLK1 plays a role in regulating Notch signaling activity which is involved in DM complications such as retinopathy, nephropathy, neuropathy, and cardiomyopathy." (PMID 39845838, 2024). "Our study demonstrates a novel role and a pro-inflammatory mechanism of macrophage DCLK1 in obesity-induced cardiomyopathy and identifies DCLK1 as a new therapeutic target for the treatment of this disease." (PMID 37443105, 2023). "By controlling the RIP2/TAK1 signaling pathway and macrophage activation, we discovered that DCLK1 has a detrimental impact on obesity-induced cardiomyopathy." (PMID 37443105, 2023). "To understand how macrophage-specific DCLK1 regulates obesity-induced cardiomyopathy, we carried RNA sequencing of the cardiac tissues from various mice groups." (PMID 37443105, 2023). "Herein, we showed that DCLK1 was overexpressed in the cardiac tissue of obese mice and investigated the role of DCLK1 in obesity-induced cardiomyopathy." (PMID 37443105, 2023). "Inhibition of DCLK1 with pharmacological agents significantly mitigates cardiomyopathy in mice fed an HFD." (PMID 37443105, 2023). "Our research demonstrates a novel role of DCLK1 and identifies DCLK1 as a new treatment target for obesity-induced cardiomyopathy." (PMID 37443105, 2023). "This research reports that macrophage-specific DCLK1 performs a key part in obesity-related inflammation and cardiomyopathy." (PMID 37443105, 2023). "Additionally, a separate study revealed that DCLK1 plays a role in obesity-induced cardiomyopathy, indicating that its impact extends beyond DM." (PMID 39845838, 2024). "Then, we investigated the role of DCLK1 in obesity-induced cardiomyopathy." (PMID 37443105, 2023). "Similarly, knockout of doublecortin-like kinase 1 (DCLK1) in macrophages attenuated RIP2/TAK1 signaling, suppressing inflammatory macrophage activation and protecting against obesity-induced cardiomyopathy." (PMID 41346626, 2025).
fibrosis (3 papers, 2022 to 2025). the formation of excess fibrous connective tissue in an organ or tissue in a reparative or reactive process. "In tumor biology, it is involved in the development of multiple malignant tumors as a pro-cancer factor; in obesity models, DCLK1 promotes myocardial fibrosis by activating the RIP2/TAK1 pathway, suggesting that it may affect fat metabolism by regulating the inflammatory microenvironment." (PMID 41463391, 2025).
helminth infection (3 papers, 2018 to 2024). "Gastrointestinal DCLK1+ tuft cells constitutively express IL-25, and its expression is further increased after helminth infection, leading to IL-13 secretion by ILC2s." (PMID 38061015, 2024). "Gastrointestinal DCLK1+ tuft cells constitutively express IL-25, and its expression is further increased after helminth infection, leading to IL-13 secretion by type 2 innate lymphoid cells (ILC2s)." (PMID 38061015, 2024).
kidney cancer (3 papers, 2020 to 2021). Primary or metastatic malignant neoplasm involving the kidney. "For instance, DCLK1-ASVs, as an alternate splice variant of DCLK1, plays a stem cell supportive role in kidney cancer via driving self-renewal and drug resistance to chemotherapy." (PMID 33783315, 2021). "Previous reports indicate that DCLK1 is overexpressed in pancreatic, colorectal, and kidney cancers." (PMID 31979136, 2020).
liver cancer (3 papers, 2015 to 2023). An epithelial or non-epithelial malignant neoplasm that arises from the liver. "The role of DCLK1 in the regulation of pluripotency in the liver cancer context is novel and may present an exciting new target for anti-cancer therapy." (PMID 26468984, 2015). "Here, we investigated whether DCLK1 negatively regulates miR-143/145 in liver cancer." (PMID 26468984, 2015). "Furthermore, DCLK1 may also be used as a prognostic biomarker for liver cancer." (PMID 26468984, 2015).
liver diseases (3 papers, 2013 to 2024). "DCLK1 protein levels in the sera of 270 test subjects were analyzed to determine the possible association between DCLK1 expression and the observed stage of liver disease." (PMID 38928187, 2024). "In summary, our study highlights the need to explore DCLK1’s role in distinguishing between pre-neoplastic liver disease and HCC amid chronic inflammation." (PMID 38928187, 2024). "Here, we describe differentially expressed miRNAs in liver disease, the expression of some correlated with DCLK1 expression levels, and represent potential therapeutic targets for liver disease." (PMID 38928187, 2024). "Given DCLK1’s role in inflammatory liver diseases, tumorigenesis, and metastasis, we investigated stage-specific miRNA expression in patients with high (40–60 ng/mL) and low (2–20 ng/mL) DCLK1 levels." (PMID 38928187, 2024). "These latter results combined with the data presented here offer a potential novel mechanism of action for the beneficial effects of FLV against HCV and HCV-induced liver diseases via interaction with the DCLK1-microtubule axis." (PMID 24260365, 2013). "The consistent DCLK1 expression across different stages of liver disease may be due to its stable roles in stem cell regulation, inflammation, and tumorigenesis." (PMID 38928187, 2024). "DCLK1-mediated miR-1246 increase likely promotes liver disease progression." (PMID 38928187, 2024). "Having established that DCLK1 is elevated in sera from liver disease patients, we sought to investigate downstream effectors of elevated DCLK1, as well as other potential markers, in order to distinguish the various stages of liver disease." (PMID 38928187, 2024). "This indicates that, while DCLK1 serum levels are elevated in chronic liver disease, they do not differentiate between progressive stages of liver disease." (PMID 38928187, 2024). "However, we did not observe any statistically significant differences in DCLK1 protein levels between patients with the different stages of progressive liver disease." (PMID 38928187, 2024).
melanoma (3 papers, 2018 to 2019). A malignant, usually aggressive tumor composed of atypical, neoplastic melanocytes. "There was increased expression of DCLK1 in human cancers (Kidney, CRC, Liver, Esophagus, Bladder, Cervix, Uterus, Rectal, Lung, Ovary, Melanoma, and Breast) compared to human normal tissues." (PMID 31878090, 2019).
Obesity (3 papers, 2023 to 2025). Accumulation of substantial excess body fat. "Doublecortin-like kinase 1 (DCLK1) is an important target for cancer therapy and the role of DCLK1 in obesity and cardiovascular diseases is unclear." (PMID 37443105, 2023). "The potential involvements of DCLK1 in obesity and other obesity-induced diseases are interesting and deserve further research." (PMID 37443105, 2023). "Herein, we demonstrated that the RIP2-TAK1 signaling pathway in macrophages is activated by DCLK1 during obesity, and this activation is independent of NOD1/2." (PMID 37443105, 2023). "However, the role of DCLK1 in obesity and cardiovascular diseases has not yet been studied." (PMID 37443105, 2023).
virus infection (3 papers, 2019 to 2024). "Doublecortin-like kinase 1 is an important target in various virus infection and tumorgenesis processes." (PMID 39682415, 2024).
Anxiety (2 papers, 2022). Intense feelings of nervousness, tension, or panic often arise in response to interpersonal stresses. "Of note, DCLK1 (isoform-) expression is associated with cognitive abilities and anxiety." (PMID 35274098, 2022).
cardiac hypertrophy (2 papers, 2023 to 2024). "The heart tissues of mice given an HFD were shown to have hypertrophic alterations when inspected grossly and when dyed with WGA; whereas, DCLK1-IN treatment significantly reduced the HFD-induced cardiac hypertrophy in the mice." (PMID 37443105, 2023). "Both the visual inspection of the whole heart and WGA staining of heart tissue slices revealed hypertrophic alterations in DCLK1f/f-HFD group mice, while macrophage-specific DCLK1 knockout mice exhibited significantly reduced HFD-induced cardiac hypertrophy." (PMID 37443105, 2023). "Myeloid cell-specific DCLK1 deletion or pharmacological inhibition of DCLK1 reduced cardiac hypertrophy and fibrosis, thereafter, restored heart function in HFD-fed mice." (PMID 37443105, 2023). "We generated DCLK1-deleted mice and showed that macrophage-specific DCLK1 knockout, rather than cardiomyocyte-specific DCLK1 knockout, prevented high-fat diet (HFD)-induced heart dysfunction, cardiac hypertrophy, and fibrosis." (PMID 37443105, 2023). "Interestingly, we found that macrophage- but not cardiomyocyte-specific DCLK1 knockout prevented HFD-induced cardiac hypertrophy and fibrosis." (PMID 37443105, 2023).
Chronic colitis (2 papers, 2025). A chronic inflammatory disease of the large intestine (colon, cecum and rectum). "DCLK1 (also known as DCAMKL1) is mainly expressed in tuft cells, and has been linked to inflammatory responses to pathogens, but has also been suggested to ameliorate chronic colitis in a mouse model." (PMID 40986406, 2025).
diabetes (2 papers, 2008 to 2025). "Doublecortin-like kinase 1 (DCLK1), a microtubule-associated protein supporting neuronal survival and synaptic development, which is understudied in diabetes, regulates Notch signaling and may influence diabetic neuropathy." (PMID 40508141, 2025).
ductal adenocarcinoma (2 papers, 2015). "The gene data sets 5-LOX activating protein (FLAP), 5-LOX, mPGES-1, mPGES-2, EGFR, and DclK1 were significantly decreased by the combination treatment during the progression of pancreatic lesions to ductal adenocarcinoma." (PMID 26429877, 2015). "Genome-wide transcriptome analysis of normal pancreas and ductal adenocarcinoma revealed that the mRNAs of COX-2, 5-LOX and DclK1 were increased significantly (up to 53-fold; p < 0.01–0.001) in the PDAC." (PMID 25906749, 2015).
head and neck cancer (2 papers, 2021). A primary or metastatic malignant neoplasm affecting the head and neck. "In this study, we used bioinformatics, immunohistochemistry, and cell physiology assays in combination with overexpression and siRNA-knockdown to study the role of DCLK1 in head and neck cancer." (PMID 34336664, 2021).
hyperlipidemia (2 papers, 2023). "Another unanswered question arising from our study is how oxLDL/hyperlipidemia upregulates DCLK1 in macrophages." (PMID 36896602, 2023). "Although our study focused on the heart, our data also showed that DCLK1 deletion in macrophages or pharmacological inhibition significantly reversed hyperlipidemia profile in HFD-fed mice, suggesting that DCLK1-mediated macrophage activation plays a role in lipid metabolism." (PMID 37443105, 2023). "Feeding mice with a HFD for 16 weeks significantly increased the body weight and induced hyperlipidemia in ApoE−/−DCLK1f/f mice compared to the low‐fat diet (LFD) group, while macrophage‐specific DCLK1 deletion did not affect the increased body weight and serum lipid profile in HFD‐fed ApoE−/− mice." (PMID 36896602, 2023).
infectious colitis (2 papers, 2021). A viral or bacterial infectious process affecting the large intestine. "To begin to understand the mechanistic basis of DCLK1–Notch axis in vivo, we utilized a well-established model of infectious colitis." (PMID 34226497, 2021). "Employing this well-credentialed model of infectious colitis, we previously demonstrated that chronic inhibition of Notch signaling coupled with decreases in DCLK1+ cells result in severe inflammation, morbidity, and mortality in an outbred strain that otherwise exhibits a self-limiting disease." (PMID 34226497, 2021). "To this end, we did, however, see moderate increase in DCLK1+ cells in Rag-1−/− mice treated with antibiotics suggesting that restoring crypt DCLK1 may help attenuate infectious colitis." (PMID 34226497, 2021). "Since DCLK1 was significantly overexpressed in Rag-1−/− mice in response to CR infection, we further bred DCLK1fl/fl;CDX2-Cre/ERT2 mice with Rag1−/− to generate double knockout (DKO) mice to see whether the DKOs are more susceptible to infectious colitis." (PMID 34226497, 2021).
intestinal polyp (2 papers, 2013 to 2015). Discrete abnormal tissue masses that protrude into the lumen of the intestine. "A recent study also demonstrated that ablation of Dclk1+ cells in Apcmin/+ mice resulted in regression of intestinal polyps, without affecting normal intestinal homeostasis." (PMID 26468984, 2015). "A recent report has also shown that Dclk1 can distinguish between normal and tumor stem cells in Apcmin/+ mice and that ablation of Dclk1+ cells resulted in regression of intestinal polyps without affecting homeostasis." (PMID 24040120, 2013). "Additionally, a recent study has demonstrated that ablation of Dclk1+ cells in Apcmin/+ mice resulted in regression of intestinal polyps without affecting the normal intestinal homeostasis." (PMID 24040120, 2013).
invasive breast carcinoma (2 papers, 2016 to 2019). A carcinoma that infiltrates the breast parenchyma. "Here, the expression of DCLK1 was analyzed in a large cohort of invasive breast cancers (IBC) by immunohistochemistry." (PMID 26621833, 2016).
lung fibrosis (2 papers, 2022). "Recently, it has also been found that IL-17 drives the induction of DCLK1 expression in a bleomycin-lung fibrosis mice model and pancreatic intraepithelial neoplasia cells." (PMID 36369000, 2022). "Based on the evidence that epithelial cells differentiate into myofibroblasts through the EMT and that myofibroblasts promote lung fibrosis, DCLK1 and STK33 may serve as therapeutic candidates for IPF." (PMID 35130915, 2022). "Moreover, IL-17 drives the upregulation of DCLK1 expression in a bleomycin-induced lung fibrosis mice model and pancreatic intraepithelial neoplasia cells." (PMID 36369000, 2022).
malignant mesothelioma (2 papers, 2021 to 2022). A malignant neoplasm of the pleura or peritoneum, arising from mesothelial cells. "XMD8-92 decreased tumor sphere formation and invasion via doublecortin-like kinase 1 (DCLK1) downregulation in malignant mesothelioma cell lines in vitro." (PMID 33572742, 2021).
metastatic tumors (2 papers, 2015 to 2016). "In these two cases, DCLK1 expression was much higher in the metastatic tumor than in the primary tumor." (PMID 26764906, 2016). "In the present study, we found high expression levels of DCLK1 in clinical samples from two different types of metastatic tumors (liver and lung)." (PMID 26764906, 2016). "These six pairs of primary and metastatic tumors were evaluated for the expression of DCLK1." (PMID 26764906, 2016). "Interestingly, cancer cells that were positively stained for DCLK1 protein were rarely detected in the primary tumors, but were clearly detected in metastatic tumors, and in all cases, the staining score was higher in metastatic tumors than in primary tumors." (PMID 26764906, 2016). "In addition, Dclk1 is co-localized with YFP in both primary and metastatic tumors of these KPCY mice." (PMID 25723399, 2015).
ovarian clear cell cancer (2 papers, 2019 to 2021). An invasive malignant neoplasm that arises from the ovary and is characterized by a predominance of clear and hobnail malignant epithelial cells. "In accordance with our findings, miR-424 was previously illustrated to be poorly-expressed in ovarian clear cell carcinoma, and further exhibited an inhibitory role on malignant phenotypes in ovarian clear cell carcinoma via doublecortin-like kinase 1 suppression." (PMID 33407591, 2021).
prostate tumors (2 papers, 2013 to 2023). "The specificity of DCLK1 staining prompted us to further analyze DCLK1 expression in prostate tumors." (PMID 37386128, 2023). "Overexpression of DCLK1 has also been detected in breast, pancreas and prostate tumors." (PMID 24086625, 2013).
amyotrophic lateral sclerosis (1 paper, 2023). Amyotrophic lateral sclerosis (ALS) is a neurodegenerative disease characterized by progressive muscular paralysis reflecting degeneration of motor neurons in the primary motor cortex, corticospinal tracts, brainstem and spinal cord. "(G) RNA-seq data from the Target Amyotrophic Lateral Sclerosis (ALS) dataset of post-mortem lumbar spinal cords were analyzed for DCLK1 (left) and TXNIP (right) counts." (PMID 36951542, 2023).
anemia (1 paper, 2021). A reduction in the number of red blood cells, the amount of hemoglobin, and/or the volume of packed red blood cells. "However, considering that ruxolitinib has many side effects such as thrombocytopenia, anemia, and neutropenia and shows a low binding affinity for DCLK1, the development of new inhibitors that are selective and potent for DCLK1 should be directed." (PMID 34445192, 2021).